VIM (vimentin)
Diseases named in the same sentence as VIM in open-access papers (continued):
Sharing a sentence is not in itself a finding about the gene and the disease.
tumor (continued). "The decreased E-cadherin and increased vimentin expression were proposed to be linked to the increased mobility of tumor cells, leading to a higher risk of metastasis in patients diagnosed with HNSCC." (PMID 38611032, 2024). "A low SVM_Score also tends to have higher Ki67 positive and increased expression of Vimentin and indicates that SVM_Score is associated with tumor proliferation and EMT propensity in our in-house LUAD patients cohort." (PMID 38987529, 2024). "Taken together, these findings indicate that KEAP1-259aa encoded by circKEAP1 acted as a tumor suppressor by suppressing vimentin." (PMID 38383479, 2024). "The effectiveness of BP1003 is likely due to its ability to decrease STAT3 levels, which leads to decreased expression of its downstream targets, such as vimentin and Bcl-2, which have both been associated with tumor aggression and poor prognosis." (PMID 39200368, 2024). "High expression of vimentin (an indicator of EMT) in tumor tissue biopsies was identified as an independent risk factor for a high CTC count in peripheral blood." (PMID 37914786, 2023). "Increased expression of vimentin in cancer cells is associated with enhanced tumor growth and invasiveness." (PMID 37511550, 2023). "The T1 and T2 tumor cells were also different in terms of the expression of epithelial markers (EpCam, E-Cadherin), mesenchymal markers (Vimentin, Pdgfra) and dormancy associated marker (Nr2f1) as shown by the qRT-PCR analysis." (PMID 37841442, 2023). "In our study, the change in the expression pattern of Cx37, Cx40, pannexin-1, and vimentin was not only associated with different pathological stages (suggesting their possible role in tumor suppression), but also had a significant diagnostic/prognostic role." (PMID 36833374, 2023). "Circulating tumor cells (CTCs) present a valuable model to examine EMT-associated genes such as vimentin, E-cadherin, and N-cadherin." (PMID 38002286, 2023). "Vimentin is a marker of mesenchymal phenotype and has been associated with tumour migration and invasion." (PMID 36765531, 2023). "Overexpression of VIM has been consistently associated with key features of tumor progression, including invasion, metastasis, and resistance of tumor cells." (PMID 38098487, 2023). "Higher expression of N-cadherin, Vimentin, Snail, and Sox2 and lower expression of E-cadherin are always associated with tumor metastasis." (PMID 37745054, 2023). "Together, these data indicate that loss of vimentin suppresses tumor development in a murine model of LUAD, contributing to prolonged survival." (PMID 37161053, 2023). "The EMT phenotype, which consists in the expression of epithelial markers and vimentin (epithelial+/vim+), is considered a tumor hallmark." (PMID 37444476, 2023). "Among the related proteins involved in EMT progression, a loss of E-cadherin and overexpression of vimentin are generally indicative of invasive tumor behavior and distant metastasis." (PMID 36611072, 2023). "GFAP+ or Vimentin+ SCs were closely associated with cancer cells by infiltrating in tumour stroma (higher magnification images)." (PMID 37830980, 2023). "It has been shown that increased density of CD68+ tumor-associated macrophages (TAMs) is associated with increased vascular and lymphatic invasion in HNSCC, and Vimentin is known to be associated with tumor growth and metastasis in cancer." (PMID 37387167, 2023). "Vimentin suppresses cell differentiation, regulates pluripotent potential, and increases the stemness of cancer cells, promoting tumor invasiveness and causing resistance to therapy." (PMID 36833374, 2023). "This is exemplified by a ten-day contact co-culture of NFs with tumor cells, where the fibroblasts induce EMT in the tumor, with characteristic loss of E-cadherin, induction of vimentin, tumor growth, and metastatic potential in vivo." (PMID 37046676, 2023).
tumor (continued). "Of note, TGFβ signaling was shown to promote EMT, which is manifested by the loss of E-Cadherin and increased expression of SOX9 and Vimentin, thus promoting tumor invasion in NSCLC." (PMID 37085672, 2023). "ECM1 upregulation was associated with a significant increase in both tumor volume and weight (–C), while Western blotting revealed increased Vimentin expression and reduced E-cadherin expression in ECM1-overexpressing tumors." (PMID 35574325, 2022). "E-cadherin, which was commonly thought to be inversely correlated with N-cadherin and deficient in tumor cells, was unexpectedly down-regulated in spite of the downregulation of N-cadherin and Vimentin." (PMID 36297592, 2022). "Protein expression levels were assessed for α-SMA, Vimentin, and FN, markers of tumor aggressiveness associated with epithelial-mesenchymal transition (EMT)." (PMID 36299463, 2022). "Numerous findings show that upregulation of TROP2 is associated with EMT induction in various tumor cell types, as evidenced mainly by decreased E-cadherin levels and increased vimentin expression, while some authors reported the opposite effect." (PMID 36077674, 2022). "Unexpectedly, PD-1+ cell expression was associated with longer OS when combined with snail+vimentin+ tumour cells, therefore further investigation is needed." (PMID 36358805, 2022). "Quantitatively, vimentin-positive, spindle-like cells exhibited increased Z1 intensity relative to E-cadherin-positive cells or vimentin-positive, rounded cells (likely tumor-associated macrophages) (P < 0.0001, see Methods for details)." (PMID 36192379, 2022). "Vimentin is linked to increased tumor growth and invasiveness and considered to be a major biomarker of EMT55." (PMID 36446776, 2022). "The extent of vimentin expression in cells of the tumor stroma is associated with the conditions within the tumor microenvironment." (PMID 35150409, 2022). "In animal studies, the overexpression of DYRK2 was associated with impaired tumor growth, in addition to inhibiting Twist and Vimentin expression while enhancing Vimentin expression within CRC xenograft tumors." (PMID 36577753, 2022). "The positive vimentin expression was found to be associated with increased stage, size of the tumor, treatment failures, locoregional recurrence, and poorer disease-free survival." (PMID 35498535, 2022). "Snail is linked to tumour progression and invasiveness due to its ability to alter the expression of the Vimentin gene (vim)." (PMID 35884609, 2022). "Expression of the proteins' characteristic of mesenchymal cells (N-cadherin and vimentin) and loss of epithelial markers (E-cadherin) correlate with tumor progression and poor prognosis." (PMID 35942366, 2022). "Pioneering studies have shown that tumor cells with the propensity for invasion display loss of surface E-cadherin and upregulation of N-cadherin and vimentin, the typical characteristics of EMT phenotype." (PMID 36497402, 2022). "In TSCC, an interesting link between EMT and tumor “budding” was studied, demonstrating that high-intensity tumor budding is associated with reduced E-cadherin expression and enhanced vimentin expression." (PMID 36669020, 2022). "Within the CGGA cohort, CASZ1 mRNA level was positively associated with tumor proliferation index Ki‐67 (r = 0.285, p < 0.0001) and invasion index vimentin levels (r = 0.457, p < 0.0001)." (PMID 36276925, 2022). "RT-PCR analysis of EMT-associated factors showed that the orthotopic tumor had an increased expression of EMT-associated factors Vimentin, Twist, ZEB1, SNAIL and ZEB2 as compared to metastatic tissues." (PMID 35837106, 2022). "In our study, we found that the loss of tumor cells’ integrality by tumor budding together with vimentin expression vividly promotes the EMT." (PMID 36143062, 2022).
tumor (continued). "We also observed the changes in EMT-associated signaling (E-cadherin, vimentin and Slug) in the tumor tissue treated with PI3K-α inhibitor, where the EMT signaling was inhibited significantly." (PMID 35536306, 2022). "In the BT-549 model, reactivation of epithelial properties mediated by PRRX1 loss, upregulation of E-cadherin, and loss of Vimentin resulted in tumor-initiating ability and MET, followed by formation of the metastatic foci in lungs." (PMID 34063254, 2021). "DHA reversed EMT changes in tumor tissues, causing E-cadherin and p-Ezrin reinventing and the re-inhibition of Vimentin, N-cadherin, Snail, and Twist expression compared to the model group." (PMID 34539408, 2021). "The EMT process is tightly linked to tumor cell invasion and metastasis, and it is characterized by E-cadherin downregulation and elevated N-cadherin and Vimentin expression." (PMID 34552494, 2021). "EpCAM expression was identified as the major characteristic of retained epithelial differentiation of carcinoma cells, and loss of EpCAM expression at the edges of tumor areas was frequently accompanied by expression of the mesenchymal marker vimentin." (PMID 34693227, 2021). "Pathological detection of tumor tissues confirmed that the anti-cancer activities of CP were tightly associated with downregulated expressions of β-catenin, Cav-1, and Vimentin, and upregulation in the expression of E-cadherin." (PMID 34168559, 2021). "According to previous reports, the expression of vimentin protein is associated with HBx in HBV-related tumor tissues." (PMID 34830378, 2021). "Numerous studies relating to proteomics have shown that vimentin is associated with tumor growth and metastasis in multiple malignancies." (PMID 34206844, 2021). "At a cutoff of 10% Slug-positive tumors cells, tumors showed a markedly higher count of cytokeratin/vimentin double-positive tumor cells, which are considered a hallmark of EMT." (PMID 33673269, 2021). "A number of studies have confirmed that increased expression of VIM is associated with tumor metastasis and invasiveness, and is considered to be a classic marker of epithelial–mesenchymal transition (EMT)." (PMID 34372874, 2021). "The ubiquitous expression of VIM as a malignancy marker in the investigated pGCL, which identifies the cultured cells as tumor cells, underlines this." (PMID 33251771, 2021). "The aim of this study was to evaluate the diagnostic efficacy of vimentin-positive circulating tumor cells (V-CTCs) in BTCs and benign biliary diseases (BBDs)." (PMID 34640452, 2021). "Loss of CK expression and gain of VIM expression in tumor cells localized along the basal cell layers at the periphery of the islands and cords of neoplastic epithelium, consistent with EMT at the invasive fronts of the neoplasm." (PMID 34493785, 2021). "High expression levels of vimentin have been associated with increased capacity for migration and invasion of the tumor cells." (PMID 34770931, 2021). "The loss of E-cadherin and expression of vimentin in tumor tissue is associated with higher metastatic risk, and correlates with poor prognosis for HNSCC patients." (PMID 33407564, 2021). "The epithelial–mesenchymal transition (EMT) is strongly associated with tumor metastasis, and consists of several protein markers, including E-cadherin and vimentin." (PMID 34063134, 2021). "Overexpression of vimentin in canine OSA is suspected to be associated with increased tumor cell motility, invasiveness, and a more aggressive phenotype." (PMID 33807419, 2021). "Studies revealed that the high expression of E-cadherin and the low expression of Vimentin cause epithelial differentiation, which is essential for tumor metastasis and invasion." (PMID 33869039, 2021). "Upregulation of mesenchymal markers such as vimentin has been associated to tumor progression and increased invasiveness." (PMID 33671551, 2021).
tumor (continued). "Although vimentin-positive circulating tumor cells (V-CTCs) are a good candidate for diagnostic and prognostic biomarkers, studies on the topic are limited." (PMID 34640452, 2021). "Initial diagnostic immunostains of the tumor showed vimentin immunoreactivity and patchy staining for S100β." (PMID 33707600, 2021). "The VIM expression is detected in cancer cell lines and in most tumor types and is significantly associated with a poorer differentiation grade in lung cancers." (PMID 33917452, 2021). "Recent studies have shown that TGF-β and vimentin play a role in immune suppression in many human cancers and are associated with tumor dissemination, metastasis, and poor prognosis." (PMID 34830801, 2021). "A recent study showed that portal vein invasion by pancreatic cancer was seen in tumors with loss of membranous E-cadherin in tumor buds, higher expression of vimentin, activated CAF morphology, and margin positive resection." (PMID 32466266, 2020). "Positivity of N-cadherin and vimentin were seen to be associated with tumor aggressiveness, consistent with previous reports." (PMID 32300922, 2020). "We observed vimentin immunoexpression in tumor-associated stromal tissue in 99% of HPV-positive and 100% of HPV-negative tumors." (PMID 32794417, 2020). "β-catenin accumulation and the acquisition of mesenchymal markers, as Vimentin, in tumor cells, are associated with cancer cells’ ability to spread to distant sites." (PMID 33040091, 2020). "In malignant tumors, E-cadherin, an epithelial marker, is downregulated, and vimentin, an interstitial marker, is upregulated; moreover, cell adhesion is decreased, migration is enhanced, and tumor cells are more susceptible to invasion and metastasis." (PMID 33330321, 2020). "Concerning vimentin, the proportion of positively stained tumor cells > 5% and staining score ≥4 significantly associated with longer OS (p = 0.024 and 0.033, respectively)." (PMID 32731632, 2020). "Analysis of one hundred and thirty-six ESCC patient specimens disclosed that low miR-146a expression or high vimentin level was significantly associated with tumor formation and poor overall survival rate." (PMID 33248456, 2020). "Analysis of one hundred and thirty-six paired ESCC patient specimens revealed that low miR-146a and high vimentin levels were frequently detected in tumor, and that the former was associated with late tumor stages (III and IV)." (PMID 33248456, 2020). "In particular, vimentin has received attention in recent years because it has been found overexpressed in different types of tumor cells, and this overexpression is associated with an increase in cell invasion and tumor growth." (PMID 31534630, 2019). "EMT is closely associated with tumor cell migration and invasion, and overexpression of Snail and vimentin." (PMID 31508369, 2019). "Reducing of E-cadherin or increasing N-cadherin, vimentin expression is often associated with worse tumor grade and stage, which correlate with our clinical and cell investigation." (PMID 31391070, 2019). "Several studies associated the acquiring of a cytoskeleton rich in vimentin filaments by cancer cells to both the increase in tumor aggressiveness and the formation of the osteoblast-like cells." (PMID 31614564, 2019). "Vimentin and lumican have long been known as cancer-associated proteins and are involved in tumor growth and metastasis." (PMID 30440021, 2018). "In tumours of the gastrointestinal tract, overexpression of vimentin has generally been associated with an increased aggressiveness." (PMID 30248895, 2018). "Small islands of tumor cells separated from the major tumor area frequently showed loss of EpCAM expression at the edges, which was linked to gain of vimentin expression, itself suggestive of partial EMT within tumors." (PMID 30275505, 2018).
tumor (continued). "Emerging literature suggests that EMT plays a crucial role in tumor cell metastasis and invasion, which is accompanied by upregulation of mesenchymal-associated genes such as vimentin and downregulation of epithelial-associated markers such as E-cadherin." (PMID 29743885, 2018). "The histological classification of CTVT was mainly based on positive immunostaining for lysozyme (encoded by LYZ), α1-antitrypsin (encoded by SERPINA1), and vimentin (encoded by VIM) in about 30%–50% of the tumor cells." (PMID 29634949, 2018). "When comparing vimentin and E-Cad staining, it turned out that vimentin-positive tumour cells showed loss or reduction of E-Cad positivity." (PMID 29976164, 2018). "EMT is an essential event during tumor metastasis to distant sites, and is associated with tumor cells to lose epithelial makers, such as E-cadherin, while acquiring mesenchymal makers, such as vimentin and N-cadherin." (PMID 28417919, 2017). "PDAC is characterized by abundant stroma that consists of activate tumor-associated fibroblasts that express vimentin and α smooth muscle actin (α-SMA)." (PMID 29042665, 2017). "It was found an association between vimentin expression with age and tumor size; over-expression in older age and decreasing in larger tumor size." (PMID 28900381, 2017). "E-cadherin, the loss of which contributed to an EMT process and promoted tumor metastasis, was downregulated and vimentin, fibronectin, Snail and Slug were upregulated after calponin 2 knockdown in PDAC cells." (PMID 28915602, 2017). "We investigated the association between L1CAM expression and survival, as well as the association between L1CAM expression and percentage of vimentin expressing tumor cells." (PMID 29152102, 2017). "Ki-67, VEGF and Vimentin were known to be associated with tumor growth, metastasis or differentiation." (PMID 28498813, 2017). "Loss of PLEC in HEY Oct4A KD cells coincides with the loss of VIM expression also seen in tumor xenografts." (PMID 28406185, 2017). "Tumor progression is frequently associated with up-regulation of vimentin and transcription factors such as Snail, Twist, and Slug as well as down-regulation of E-cadherin." (PMID 28942499, 2017). "Percentage of vimentin expressing tumor cells was strongly associated with L1CAM expression (P = 0.003, One-way ANOVA)." (PMID 29152102, 2017). "Accordingly, FASN expression was negatively associated with tumor grade and vimentin expression, both characteristics described to be closely associated with ML tumors." (PMID 29088795, 2017). "As L1CAM expression has been related to EMT, we assessed the association between L1CAM expression and the percentage of vimentin expressing (keratin positive) tumor cells, determined by flow cytometry." (PMID 29152102, 2017). "L1CAM expression was independently associated with locoregional recurrence-free survival (hazard ratio 2.62, 95% CI 1.33 – 5.17, P = 0.006), and strongly associated with percentage of vimentin expressing tumor cells (P = 0.003)." (PMID 29152102, 2017). "As L1CAM is thought to play a role in EMT, we investigated the association between L1CAM expression and percentage of vimentin expressing tumor cells, assessed by flow cytometry." (PMID 29152102, 2017). "Third, expression levels of VIM, a marker of intermediate filament associated with poor prognosis and tumor invasion, increased." (PMID 29152094, 2017). "Despite structural differences between tumour and control networks, we found a conserved set of associations between miR-200 family members and genes such as VIM, ZEB-1/2 and TWIST-1/2." (PMID 29051564, 2017). "Elevated expression of MMPs and vimentin are associated with increased metastatic potential in many tumor cells." (PMID 28402270, 2017). "According to previous studies, E-cadherin and vimentin expression was associated with tumor stage, which was in accordance with our results." (PMID 28744307, 2017).